EGFR (epidermal growth factor receptor)
Diseases named in the same sentence as EGFR in open-access papers (continued):
Sharing a sentence is not in itself a finding about the gene and the disease.
non-small cell lung carcinoma (continued). "Determining the mutational status of KRAS is essential before initiating treatment plans for cancers such as non-small cell lung cancer (NSCLC) and colorectal cancer (CRC), particularly when considering therapies targeting the epidermal growth factor receptor (EGFR)." (PMID 41294676, 2025). "The molecular pathogenesis of lung NENs is complex and varies across the different subtypes, typically lacking common oncogenic driver mutations found in non-small cell lung cancer (NSCLC), such as KRAS and EGFR in lung adenocarcinomas." (PMID 40586102, 2025). "Epidermal growth factor receptor (EGFR) is one of the most important and therapeutically significant targets in most cancer treatments, and EGFR-targeted therapy is widely performed to treat various tumors, such as non-small cell lung cancer." (PMID 40535810, 2025). "EGFR-targeted CAR-T cell therapy has been applied in clinical trials to treat various cancers, including triple-negative breast cancer, head and neck cancer, glioblastoma, and non-small cell lung cancer, and some of them have shown promising outcomes." (PMID 40722671, 2025). "Indeed, the resistance of non-small cell lung cancer (NSCLC) to several RTK inhibitors, including those targeting EGFR-, ALK-, and MET-signaling, has been shown to result from EMT." (PMID 40943068, 2025). "A subsequent value of implementation analysis quantified how limited testing capacity for ALK mutations reduced the incremental net benefit of crizotinib for people with EGFR-negative non-small cell lung cancer." (PMID 40726112, 2025). "An example of the success of this approach is illustrated by Amivantamab (Rybrevant), which targets epidermal growth factor (EGFR) and tyrosine kinase receptors (c-MET) (EGFR x c-MET) and was approved in May 2021 for non-small cell lung cancer treatment." (PMID 41250091, 2025). "The anticancer potential of lupeol was consistently noted in EGFR-TKI-resistant H1975 cells (nonsmoking female with non-small cell lung cancer) (EGFR L858R/T790M)." (PMID 40417209, 2025). "Patients with advanced non-small cell lung cancer and programmed cell death-ligand 1 expression ≥50% received cemiplimab monotherapy (n=283), and patients with no EGFR, ALK, or ROS1 genomic aberrations received cemiplimab plus chemotherapy (n=312)." (PMID 41194933, 2025). "In this study, we utilized a matching methodology to stratify patients with stages II and III non-small cell lung carcinoma into cohorts receiving EGFR-TKIs and those not receiving TKIs." (PMID 40732366, 2025). "Monotherapy ICIs represent groundbreaking front-line treatment options for EGFR/ALK/ROS1 non-mutant non-small cell lung cancer (NSCLC) with high PDL1 expression (≥50% expression)." (PMID 40422518, 2025). "As a member of the ErbB/HER receptor family, EGFR is a transmembrane glycoprotein consisting of 1,186 amino acids, commonly found in various human cancers, including GBM, non-small cell lung cancer, and breast cancer, where it is frequently overexpressed and activated." (PMID 39506843, 2024). "As shown inFigure 1A, treatment of non-small cell lung cancer cells (A549, H1299, H1975, and PC-9) with 2-DG led to the appearance of two EGFR bands on SDS-PAGE, a slower migrated EGFR (S-EGFR) band and a fast migrated EGFR (F-EGFR) band." (PMID 39967270, 2024). "Another finding was that among AC patients, Ki values were lower in EGFR (+) patients than in EGFR (-) patients, and for some patients with non-small cell lung cancer (NSCLC) where EGFR testing is not available, Ki improved its discriminability." (PMID 38730287, 2024). "In non-small cell lung cancer (NSCLC), exosomal AREG increases the expression of RANKL, which subsequently increases the expression of osteoclastogenesis markers in pre-osteoclast by activating the EGFR pathway, promoting osteolytic bone metastasis." (PMID 38495881, 2024).
non-small cell lung carcinoma (continued). "Two ADCs (mAbE-21a and mAbE-21d) were evaluated in nude mice bearing human head and neck squamous cell carcinoma EGFR- + HSC-2 xenograft, as well as in nude mice bearing non-small-cell lung cancer (NSCLC) squamous cell H1703 xenograft (lower antigen expression)." (PMID 39201338, 2024). "This Cas-CHDC-powered electrochemical RNA-sensing technology chip successfully detects six non-small-cell lung carcinoma-related RNAs (miRNA-17, miRNA-155, TTF-1 mRNA, miRNA-19b, miRNA-210, and EGFR mRNA), with results consistent with those obtained from qRT-PCR." (PMID 39194596, 2024). "In non-small cell lung cancer, results from clinical trials have revealed that there were no survival benefits for EGFR-mutant non-small cell lung cancer (NSCLC) patients with the treatment of subsequent immunotherapy." (PMID 38310091, 2024). "Epidermal growth factor receptor (EGFR) is a prime target in therapeutic development since numerous malignancies, including colorectal carcinoma (CRC), non-small cell lung cancer (NSCLC), and head and neck squamous cell carcinoma (HNSCC), have abnormal overexpression of EGFR." (PMID 38610932, 2024). "Decreased cancer cell proliferative activity has been shown in non-small cell lung cancer and breast cancer when anti-IL6 antibodies were combined with EGFR small molecule inhibitor Erlotinib and anti-Human Epidermal Growth Factor Receptor (HER2) monoclonal antibody Trastuzumab, respectively." (PMID 39766086, 2024). "Indeed, integrins potentiate the EGF-dependent EGFR activation in various cells, including human foreskin fibroblasts, ECV304 endothelial cells, A549 non-small cell lung cancer cells, and the SK-MES1 lung squamous carcinoma cells." (PMID 39594667, 2024). "It was instrumental in identifying potential MTDLs targeting the epidermal growth factor receptor (EGFR) and ALK tyrosine kinase receptor (ALK) in non-small-cell lung cancer (NSLC), as well as pan-agonists for dopamine receptors (DRD1–DRD5) for the treatment of neurodegenerative diseases." (PMID 39125808, 2024). "There have been reports of coexisting mutations in the epidermal growth factor receptor (EGFR) and anaplastic lymphoma kinase (ALK) fusion genes in non-small cell lung cancer, but case of EGFR mutation following an ALK mutation has not been mentioned." (PMID 39147711, 2024). "As for Osimertinib, it is an irreversible third-generation epidermal growth factor receptor (EGFR) tyrosine kinase inhibitor (TKI) approved by the FDA and EMA as therapy for metastatic EGFR-mutant non-small-cell lung cancer (NSCLC) patients that have acquired the EGFR T790M resistance mutation." (PMID 38391832, 2024). "Despite the impressive clinical response rate of osimertinib, a third-generation EGFR-TKI, as a frontline treatment for patients with EGFR-mutant non-small-cell lung cancer (NSCLC) or as a salvage therapy for patients with T790M mutation, resistance to osimertinib is common in the clinic." (PMID 36817465, 2023). "Kaempferol may regulate EGFR/PI3K/AKT and IGF1R/PI3K/AKT signaling pathways by targeting EGFR, IGF1R, PIK3R1 and Akt, and then play a role in the treatment of non-small cell lung cancer." (PMID 37533633, 2023). "Health Canada approved pembrolizumab in the first-line setting for advanced non-small-cell lung cancer with PD-L1 ≥ 50% and no EGFR/ALK aberration." (PMID 37366902, 2023). "Additionally, non-small cell lung cancer NCI-H358 cells, which overexpress EGFR, undergo significantly greater apoptosis when treated with the CXCL12–Ctx KineTAC than when treated with Ctz IgG." (PMID 36138170, 2023). "It was 1.2% among 255 adenocarcinoma and 246 non-small cell carcinomas without EGFR/ALK aberrations." (PMID 37374289, 2023). "This study was conducted to estimate the indirect cost of locally advanced and metastatic non-small cell lung cancer (NSCLC) without sensitizing EGFR and ALK alterations in China and explore the predictors from both patient and caregiver perspectives." (PMID 36056953, 2023).
non-small cell lung carcinoma (continued). "Furthermore, combining the EGFR inhibitor, erlotinib, with the VEGFR inhibitor, bevacizumab, has also been shown to improve survival rates in advanced cases of non-small cell lung cancer." (PMID 37760616, 2023). "Amlodipine significantly suppressed the level of p-EGFR in non-small-cell lung cancer comparatively with the untreated control group, with no change detected in total EGFR." (PMID 36831338, 2023). "Herein, inspired by the work of the Nathanael S. Gray Group at Harvard Medical School, we report our study on the design, synthesis, and evaluation of new EGFR/ALK dual-target inhibitors containing sulfoxide and a cyclopropyl group for the treatment of non-small-cell lung cancer." (PMID 36903251, 2023). "For example, the potential efficacy of epidermal growth factor receptor (EGFR) inhibitors was reported for non-small cell lung cancer, but it was concluded that EGFR inhibitors were not appropriate as single agents for advanced AML." (PMID 37367084, 2023). "Notably, in non-small cell lung cancer cell models, elevated levels of EHD1 correlated with insensitivity to EGFR inhibition and such insensitivity was overcome by genetic depletion of EHD116." (PMID 37474760, 2023). "In addition, inhibition of the MAPK pathway using EGFR and MEK inhibitors prevented expression of PD-L1 at the transcriptional and translational levels in non-small cell lung cancer (NSCLC)." (PMID 37345111, 2023). "Osimertinib, a third-generation EGFR-TKI, is widely used to treat non-small-cell lung cancer." (PMID 37371780, 2023). "In addition, in non-small cell lung cancer, KCNN4 channel blocking improves the response to the EGFR inhibitor gefitinib." (PMID 37408210, 2023). "Depending on the type of cancer, certain biomarker tests are needed in order to decide on a treatment strategy (e.g., RAS/BRAF testing for colorectal cancer; an HER2 testing for gastric cancer; and EGFR, ALK, ROS1, and PD-L1 expression testing for non-small-cell lung cancer)." (PMID 37599324, 2023). "Gefitinib is a selective tyrosine kinase receptor inhibitor targeted at epidermal growth factor receptor (EGFR) alterations and has been approved in the treatment of patients with non-small cell lung cancer, and in vitro research found that it had synergistic effects with cisplatin." (PMID 35372049, 2022). "Amivantamab, available under the brand name Rybrevant, is a human IgG1-based bispecific monoclonal antibody which simultaneously targets both EGFR and the mesenchymal–epithelial transition (MET) receptor expressed on the surface of epithelial cells in non-small-cell lung cancer (NSCLC)." (PMID 36498915, 2022). "Targeting ANGPTL4 may inhibit the development of EGFR-TKI resistance, which may improve the survival rate of patients with non-small-cell lung cancer." (PMID 36467503, 2022). "Moreover, non-small cell lung cancer A549 cells that stably overexpressing STYK1 shRNA were generated and the phosphorylation levels of EGFR downstream effector were tested." (PMID 37192859, 2022). "First-line treatment for patients with metastatic non-small cell lung cancer whose tumors express PD-L1(≥1%) with no epidermal growth factor receptor (EGFR) or anaplastic lymphoma kinase (ALK) genomic tumor aberrations." (PMID 35037899, 2022). "For patients with advanced non-small-cell lung cancer (NSCLC) without targetable oncogene alterations (EGFR, ALK, ROS-1, etc.), chemotherapy used to be the best first-line treatment." (PMID 35237263, 2022). "In non-small cell lung cancer, EPAS1 bound directly to EGFR with a TKI-resistant T790M mutation; however, it did not bind to the wild-type EGFR." (PMID 36313570, 2022). "Another engineered EGFR-CAR T-cell through non-viral piggyBac system therapy in non-small cell lung cancer (NSCLC) patients was revealed to be feasible and safe (NCT03182816)." (PMID 35887150, 2022).
non-small cell lung carcinoma (continued). "The sustained activation of EGFR is largely dependent on CBLC-mediated ubiquitination, and its dysregulation is preferentially destined for membrane recycling, which plays an important role in non-small-cell lung carcinoma (NSCLC) progression." (PMID 35874839, 2022). "Inhibition of the epidermal growth factor receptor (EGFR) by EGCG resulted in potent anti-tumor effects as demonstrated by the inhibition of cell proliferation and migration in non-small cell lung cancer cells, reduced colorectal cancer cell growth, or reduced invasion of breast cancer cells." (PMID 36613784, 2022). "A multicenter survey in China found that only two thirds of EGFR positive patients with unresectable Stage IIIB/IV nonsquamous non-small cell lung cancer received tyrosine kinase inhibitors treatment." (PMID 34273922, 2022). "In January 2021, tiragolumab (anti-TIGIT) combined with atezolizumab was approved by FDA for the treatment of metastatic non-small cell lung cancer patients with PD-L1 but without EGFR/ALK genome abnormalities." (PMID 35875070, 2022). "Finally, it was reported that AFA induced apoptosis in non-small cell lung carcinoma (NSCLC) cells without EGFR mutation." (PMID 35752861, 2022). "The epidermal growth factor receptor (EGFR) is frequentlymutatedin human cancer, most notably non-small-cell lung cancer and glioblastoma.While many frequently occurring EGFR mutations are known to conferconstitutive EGFR activation, the situation is less clear for rarelydetected variants." (PMID 36148499, 2022). "Although the EGFR inhibitor gefitinib was effective in the treatment of non-small cell lung cancer, it was not efficacious in GBM." (PMID 35572524, 2022). "Osimertinib, a third-generation epidermal growth factor receptor tyrosine kinase inhibitor (EGFR-TKI) first-line therapy, has shown good clinical outcomes in non-small cell lung cancer (NSCLC), but some serious adverse events such as cardiotoxicity have also been reported." (PMID 35677717, 2022). "For example, very recent work by Swanton and colleagues has identified a potentially powerful mechanism through which PM2.5 can contribute to non-small cell lung cancer (NSCLC) in non-smokers, a disease with a high frequency of EGFR mutations (EGFRm)." (PMID 36430011, 2022). "In non-small cell lung cancer, LINC00665 upregulates EZH2, an important component of the initiation complex (PRC2), thereby activating the PI3K/AKT signaling pathway and mediating EGFR expression, weakening the inhibition of EGFR kinase by the drug gefitinib." (PMID 35563845, 2022). "A previous study by our laboratory demonstrated that DYRK1A could regulate STAT3/EGFR/MET signalling and sensitize EGFR wild-type non-small cell lung cancer (NSCLC) cells to AZD9291, thus indicating that DYRK1A could regulate EGFR via STAT3." (PMID 35655269, 2022). "Gefitinib, an EGFR inhibitor, is widely used in the treatment of non-small cell lung cancer but not cardiovascular disease." (PMID 36286305, 2022). "The epidermal growth factor receptor (EGFR) inhibitor erlotinib, a key drug in the clinical treatment of small cell lung cancer, was found to have an off-target effect in activating mitochondrial metabolic function in non-small cell lung cancer." (PMID 36089608, 2022). "Comparison of epidermal growth factor receptor tyrosine kinase inhibitor (EGFR-TKI) monotherapy or with bevacizumab in real-world non-small cell lung cancer (NSCLC) patients was lacking." (PMID 35292755, 2022). "RET is a new driver gene discovered after EGFR and ALK in non-small cell lung cancer." (PMID 35211155, 2022). "Epidermal growth factor receptor (EGFR), a cell surface receptor tyrosine kinase, is commonly overexpressed in a variety of solid tumors, including colorectal cancers and non-small cell lung cancers, and is an attractive anticancer therapeutic target against solid tumors." (PMID 36555466, 2022).
non-small cell lung carcinoma (continued). "Osimertinib, a third-generation EGFR-TKI, has nowadays been applied to non-small cell lung cancer harboring activated EGFR mutation with or without T790M, but ultimately develop resistance to this drug." (PMID 35643725, 2022). "This research shows that pembrolizumab monotherapy can be extended as a first-line therapy to patients with locally advanced or metastatic non-small cell lung cancer without sensitizing EGFR or ALK alterations and with low PD-L1 TPS." (PMID 35159131, 2022). "A phase II trial examined the combination of Seribantumab with Erlotinib or Erlotinib as a monotherapy in advanced, EGFR wild-type non-small-cell lung cancer who had not received any TKIs targeting EGFR." (PMID 36551663, 2022). "Finally, statins can overcome the resistance to EGFR tyrosine kinase inhibitors in a non-small cell lung cancer cells and to gefitinib in KRAS-mutant human non-small cell lung cancer cells." (PMID 33718197, 2021). "Activating EGFR mutant kinase were detected using 18F-MPG in patients with non-small cell lung cancer (NSCLC) and it was demonstrated that patients with a high uptake of 18F-MPG (SUV > 2.23) had a greater response to EGFR-TKIs (>80% versus 6%) and twice longer median progression-free survival." (PMID 33915894, 2021). "The epidermal growth factor receptor (EGFR) represents an important signalling pathway that regulates tumorigenesis and cell survival and is frequently overexpressed in the development and progression of non-small cell lung cancer (NSCLC)." (PMID 35047063, 2021). "Gefitinib (Iressa) is an inhibitor of EGFR-tyrosine kinase that inhibits EGFR-dependent but not IL-6-dependent phosphorylation of STAT3, and is clinically used to treat non-small cell lung cancer patients with EGFR-activating mutations." (PMID 33392396, 2021). "Our previous economic assessment found that nivolumab was not cost-effective for Chinese patients with advanced non-small cell lung cancer (NSCLC) and without EGFR mutations or ALK translocations, when compared with the standard second-line drug docetaxel." (PMID 34966668, 2021). "Instead, the majority of these 13 pathways were notably cancer-related, including ErbB signaling pathway, mTOR signaling pathway, glioma, HIF-1 signaling pathway, non-small cell lung cancer, breast cancer, choline metabolism in cancer as well as EGFR tyrosine kinase inhibitor resistance." (PMID 34272396, 2021). "In this study, the cBioPortal.org platform was tested and its utility demonstrated by comparing cases of non-small cell lung cancer (NSCLC) with and without epidermal growth factor receptor gene (EGFR) mutations." (PMID 34055528, 2021). "A comparison of an adnectin-based CAR and an scFv-based CAR showed that adnectin-based EGFR-targeted CARs have similar efficacy in targeting EGFR+ cells when compared to an scFv-based EGFR CAR in both in vitro and in non-small cell lung cancer xenograft murine models." (PMID 35011583, 2021). "JWH-105 inhibited EMT in non-small cell lung cancer cells (NSCLC) by suppressing ERK and STAT-3 activation and EGFR signaling; in addition, JWH-105 reduced invasiveness of A549 cells when co-cultured with M2 macrophages, by downregulating the expression of FAK, VCAM1, and MMP-2." (PMID 33922795, 2021). "Our previous study has revealed that pulmonary lymphoepithelioma-like carcinoma had a better prognosis compared with other types of non-small-cell lung cancer and was sensitive to radiotherapy and chemotherapy but not to targeted EGFR-TKI therapy." (PMID 31659278, 2020). "Examples include EGFR and ALK inhibitors in non-small cell lung cancer, BRAF inhibitors in melanoma, HER2-targeting agents in breast cancer, and immune checkpoint inhibitors of CTLA4 or PDL1 in melanoma or non-small cell lung cancer 6-10." (PMID 31903155, 2020).